FEV (FEV transcription factor, ETS family member)
Description:
Functions as a transcriptional regulator. According to PubMed:12761502, it functions as a transcriptional repressor. Functions in the differentiation and the maintenance of the central serotonergic neurons. May play a role in cell growth.
Synonyms: Pet-1; HSRNAFEV
Tractability: PROTAC: ubiquitination databases record sites on it.
Gene: Protein-coding gene on chromosome 2 (218,981,087 to 218,985,184, reverse strand). Ensembl gene ENSG00000163497.
Subcellular location: Nucleus
Subcellular location (Human Protein Atlas): Nuclear speckles
Gene Ontology:
Molecular function: sequence-specific double-stranded DNA binding; DNA-binding transcription factor activity, RNA polymerase II-specific; DNA-binding transcription activator activity, RNA polymerase II-specific; DNA-binding transcription factor activity; double-stranded DNA binding; RNA polymerase II cis-regulatory region sequence-specific DNA binding; sequence-specific DNA binding
Biological process: cell differentiation; regulation of transcription by RNA polymerase II; positive regulation of DNA-templated transcription; positive regulation of transcription by RNA polymerase II; regulation of DNA-templated transcription
Cellular component: nuclear speck; chromatin; nucleus
Genetic constraint (gnomAD): Loss-of-function variants: 14 observed, 16.69 expected, observed/expected ratio (o/e) 0.84, 90% interval 0.55 to 1.31. The synonymous counts are far from expectation, so gnomAD's model fits this gene poorly and the ratio says little. Missense variants: 301 observed, 278.18 expected, observed/expected ratio (o/e) 1.08, 90% interval 0.98 to 1.19. Synonymous variants: 188 observed, 139.93 expected, observed/expected ratio (o/e) 1.34, 90% interval 1.19 to 1.52.
Homologues: Orthologues: chimpanzee FEV (100% identical), macaque FEV (99% identical), dog FEV (98% identical), pig FEV (97% identical), mouse Fev (96% identical), rat Fev (96% identical), guinea pig FEV (95% identical), tropical clawed frog fev (63% identical), zebrafish fev (61% identical), rabbit FEV (57% identical). Paralogues in human: FLI1 (47% identical), ERG (45% identical), ETS2 (32% identical), ETS1 (32% identical), ELK4 (32% identical), ELK3 (31% identical), GABPA (30% identical), ELK1 (29% identical), ERF (29% identical), ETV3 (28% identical), ETV1 (27% identical), ERFL (27% identical), and 16 more.
Diseases named in the same sentence as FEV in open-access papers:
FEV is named in the same sentence as 34 diseases in open-access papers, as found by Europe PMC text mining. Sharing a sentence is not in itself a finding about the gene and the disease. The quoted sentences say what the papers report.
Ewing sarcoma (22 papers, 2010 to 2025). A small round cell tumor that lacks morphologic, immunohistochemical, and electron microscopic evidence of neuroectodermal differentiation. "FEV gene rearrangements have been observed in a fraction of Ewing sarcoma patients (3.5%) being linked to axial extraskeletal locations (mainly soft tissue), “older age at diagnosis and aggressive clinical behavior”, but retaining the classic Ewing sarcoma image." (PMID 37444135, 2023). "The FEV gene was initially cloned as a chromosomal translocation in a human Ewing tumor in a pediatric case; a portion of this gene was fused to a portion of the sequence that encoded the RNA-binding protein EWS." (PMID 35548776, 2022). "Other fusion partners seen with Ewing sarcoma include FEV, ETV1, and ETV4." (PMID 40255709, 2025). "A recent study did find a EWSR1/FEV fusion in a prostate tumor from a single patient, but it is unclear whether this tumor should be categorized as prostate adenocarcinoma or Ewing sarcoma." (PMID 34409300, 2021). "Alternatively, EWSR1 can be fused with ERG, ETV1, E1A-F (alias ETV4) or FEV in Ewing sarcoma." (PMID 29416716, 2018). "It is known that chromosomal translocations in which Ewing’s sarcoma (EWS) gene is fused to a variety of transcription factors, including human FEV, can lead to the onset of different subsets of Ewing tumours, with some of them occasionally occurring in the kidney." (PMID 25098329, 2014). "It was later reported that Ewing sarcoma has more chromosomal translocations, including EWS/FLI fusion, EWS/ERG fusion, EWS/FEV fusion, EWS/ETV1 fusion, EWS/ETV4 fusion, FUS/ERG fusion, FUS/FEV fusion, and FUS/ETV4 fusion." (PMID 36964542, 2023). "Of the 119 molecules found in common, 40 were oncogenes, including 2 Ewing sarcoma specific genes—namely, the NK2 Homeobox 2 (NKX2) and FEV transcription factor (FEV)." (PMID 37444135, 2023). "For example, Ewing sarcoma translocations involve one of five closely homologous ETS family members (FLI, ERG, FEV, ETV1, and ETV4)." (PMID 34145397, 2021). "About 3/4 of Ewing sarcoma and DSRCT tumors have an identical EWS breakpoint motif at Exon 7 (SQQSSSYGQQ-) fused to a specific part of FLI1 (NPSYDSVRRG or-SSLLAYNTSS), ERG (NLPYEPPRRS), FEV (NPVGDGLFKD) or WT1 (SEKPYQCDFK)." (PMID 36900411, 2023). "Ewing Sarcoma (ES) is a primitive small round cell sarcoma defined by fusions involving members of the FET (predominantly EWSR1 or FUS) and ETS (most commonly including FLI1, ERG, ETV1, ETV4, or FEV) gene families." (PMID 35059992, 2022). "Most Ewing sarcomas harbor gene fusions involving the FLI1, ERG, ETV1, ETV4, or FEV gene." (PMID 21789226, 2011).
depression (4 papers, 2014 to 2025). "Prenatal choline supplementation attenuated ID-induced ADORA2 gene network in women and FEV gene network in men, which are associated with depression and attention disorders, respectively." (PMID 40977974, 2025).
prostate carcinoma (3 papers, 2021 to 2023). A carcinoma that arises from epithelial cells of the prostate gland. "Specimens from tissue microarray (TMA) including 102 prostate cancer patients were analysis for the expression of FEV." (PMID 35548776, 2022).
leukemia (2 papers, 2010 to 2022). A malignant (clonal) hematologic disorder, involving hematopoietic stem cells and characterized by the presence of primitive or atypical myeloid or lymphoid cells in the bone marrow and the blood. "In our previous work, we reported that FEV is silenced in normal adult hematopoiesis and re-expressed in leukemias of prenatal origin, and FEV deficiency significantly impairs the leukemia-propagating capacity of LICs in AML patient-derived xenograft mice." (PMID 35875066, 2022). "FEV deficiency significantly reduced the engraftment of AML cells in the BM (–D), which was consistent with previous findings in leukemia with prenatal initiation." (PMID 35875066, 2022). "In previous work, we reported that FEV is silenced in adult hematopoiesis and re-expressed in leukemias of prenatal origin, such as infants, children and young adults (<40 years); we also demonstrated that FEV is essential for leukemia propagation of LICs, but the mechanism is not clear." (PMID 35875066, 2022).
autism (1 paper, 2022). Persistent deficits in social interaction and communication and interaction as well as a markedly restricted repertoire of activity and interest as well as repetitive patterns of behavior. "Pet1’s function in 5-HT neurons is clinically significant as recent studies identified biallelic loss of function of FEV, the human ortholog of Pet1, in autism cases suggesting that defects in transcriptional control of 5-HT neurons are a potential path to human neurodevelopmental disorders." (PMID 35471146, 2022).
carcinoid tumor (1 paper, 2022). A slow growing neuroendocrine tumor, composed of uniform, round, or polygonal cells having monotonous, centrally located nuclei and small nucleoli, infrequent mitoses, and no necrosis. "In the small intestine, FEV expression occurs in serotonin-producing cells in normal tissues and carcinoid tumors." (PMID 35548776, 2022).
Ewing's sarcoma family tumors (1 paper, 2008). "The EWS-FLI-1 fusion protein is associated with 85–90% of Ewing's sarcoma family tumors (ESFT), the remaining 10–15% of cases expressing chimeric genes encoding EWS or FUS fused to one of several ets transcription factor family members, including ERG-1, FEV, ETV1 and ETV6." (PMID 18648544, 2008).
hepatocellular carcinoma (1 paper, 2022). A malignant tumor that arises from hepatocytes. "Cluster 3 was enriched for LHX8 and FEV as well as DBX2, which is differentially expressed in hepatocellular carcinoma." (PMID 36404344, 2022).
tumor (7 papers, 1999 to 2024). "Functional assays revealed that FEV expression markedly inhibited PCa cell growth, migration, and invasion, which in turn significantly repressed the growth of tumor xenografts in vivo." (PMID 35548776, 2022). "The FEV-expressing PC-3 cells resulted in the formation of significantly smaller tumor nodules as well as remarkably slowed the growth of tumor xenografts relative to the controls." (PMID 35548776, 2022). "To elucidate the tumor-suppressive role of FEV in PCa, we initially established a stable cell line that overexpressed FEV after lentivector transduction." (PMID 35548776, 2022). "Our study suggests that FEV is a candidate tumor suppressor with decreased or disrupted protein or mRNA expression in PCa." (PMID 35548776, 2022). "We also investigated the part FEV plays in the growth of tumor xenografts in vivo using gain-of-function experiments." (PMID 35548776, 2022). "Neither EWS/FLI-I, EWS/ERG and EWS/FEV fusion genes nor MIC2 expression were found in any tumour, whereas trisomy 8 was found in one case only." (PMID 10574242, 1999).
cancer (3 papers, 2011 to 2024). A tumor composed of atypical neoplastic, often pleomorphic cells that invade other tissues. "ERG, ETV1, ETV4, ETV6, FLI1, and FEV, are implicated in the pathogenesis of several cancers." (PMID 21789226, 2011). "Elucidating the mechanism(s) that mediate FEV downregulation in aggressive PCa may facilitate in the identification of signaling pathways and/or coregulatory factors that could be modulated using therapeutic means to reactivate FEV expression in cancer cells." (PMID 35548776, 2022). "In the case of FAM135B, FEV, CBFB, and CTNND2, the regulatory status inferred here is at odds with their documented cancer role, thereby indicating potential anomalous regulation whose resolution would be tractable to experimental investigation." (PMID 39484215, 2024). "In cancer, the abnormal expression of oncogenic transcription factors (e.g., FLI-1 and ERG) as well as negative regulators of carcinogenesis (e.g., FEV) in the ETS family induces the upregulation of genes that are known to promote cancer and the downregulation of genes that subdue cancer." (PMID 35548776, 2022).
head and neck tumors (1 paper, 2019). "Among the most impressive differences in TF activity, head and neck tumors display lower activities of FEV, TFAP2B and GATA2 and higher activities of TFEC, LEF1, and MAFB compared to SDHD-null tumors of other anatomical locations." (PMID 31234811, 2019).
infection (1 paper, 2026). The state of being infected such as from the introduction of a foreign agent such as serum, vaccine, antigenic substance or organism. "infection significantly shifted the fEV proteome, reducing both host and microbial proteins involved in gut defence." (PMID 41540478, 2026).
neurological disorders (1 paper, 2023). "FEV is believed to regulate genes involved in early brain development and the serotonergic pathway, and MAFK is associated with numerous neurological disorders through oxidative stress response." (PMID 37533331, 2023).
FEV also shares sentences with these, for which no sentence is quoted: Anxiety (15 papers); mood disorder (2); sarcoma (2); soft tissue tumor (2); Apnea (1); desmoplastic small round cell tumor (1); diabetes mellitus (1); gastric adenocarcinoma (1); Glucose intolerance (1); insomnia (1); melanoma (1); meningioma (1); myeloid leukemia (1); myxoid liposarcoma (1); neuroblastoma (1); neurodevelopmental disorder (1); prostate adenocarcinoma (1); prostate tumor (1); sterility (1); sudden infant death syndrome (1); synovial sarcoma (1).